CRP (C-reactive protein)
Diseases named in the same sentence as CRP in open-access papers (continued):
Sharing a sentence is not in itself a finding about the gene and the disease.
Sepsis (continued). "First, it was demonstrated that measurements of presepsin levels had valuable and consistent diagnostic capacity for the different stages of sepsis severity compared to PCT, IL-6, CRP and WBC during the first week of ICU treatment." (PMID 25190134, 2014). "Many researchers have explored the predictive value of CRP for post-traumatic sepsis, but the results are unsatisfactory." (PMID 27602370, 2014). "These conditions contribute to the reduced specificity of the qualitative assay of CRP in the diagnosis of neonatal septicaemia." (PMID 25280754, 2014). "CRP is a protein produced in response to infection and/or inflammation and it is widely used in clinical tests to diagnose and manage patients with sepsis." (PMID 24800240, 2014). "The conventional markers (white blood cell count, neutrophil count and CRP) and nCD11b were found to be less useful as markers diagnosing early-onset sepsis in preterm neonates." (PMID 25033045, 2014). "The advantage of CRP includes its very low serum level in normal infants and rapid rise within 6 to 8 hours after the onset of sepsis." (PMID 25475836, 2014). "For example, C-reactive protein (CRP) is a marker of the inflammatory response post-burn and recombinant-CRP has been shown to help treating sepsis." (PMID 25489947, 2014). "Regarding CRP, the area under the ROC curve in the diagnosis of sepsis was 0.98 (95% CI 0.94–0.998), p < 0.0001, better than those of the MMPs and TIMPs." (PMID 24833564, 2014). "Serial CRP qualitative assays combined with raised WBC has high sensitivity in the diagnosis of neonatal septicaemia." (PMID 25280754, 2014). "The main explanatory variables were age, malnutrition, sepsis, C-reactive protein (CRP), and clinical severity scores." (PMID 24886623, 2014). "The sensitivities of CRP assay in the diagnosis of septicaemia using culture as gold standard on day 1, 2, 3 and any positive were 40.4%, 53.2%, 54.8% and 62.9% respectively." (PMID 25280754, 2014). "This study found that single CRP in combination with Rubarth’s neonatal scale of sepsis has a high sensitivity of 96.0% to screen for neonatal sepsis and serial CRP to be useful for excluding non-cases." (PMID 25475836, 2014). "Multivariate logistic regression analysis evaluating the independent predictive value of pentraxin 3 (PTX3), procalcitonin (PCT) and C-reactive protein (CRP) for severe sepsis." (PMID 23341967, 2013). "The computerized CRP protocol is used for determining the length of empiric antibiotic use in late-onset sepsis at our institution." (PMID 24244325, 2013). "Clinician compliance with the protocol was reasonable (72%) and subsequent suspect sepsis evaluations were infrequent in infants following the week of CRP protocol-guided cessation of antibiotics (16%)." (PMID 24244325, 2013). "Although many sepsis biomarkers have shown promise in selected patient groups, only C-reactive protein and procalcitonin (PCT) have entered clinical practice." (PMID 23531337, 2013). "The best cut-off value of CRP concentration for diagnosis of sepsis was 12.8 mg/dL, and these authors also reported a delay of 48 hours to reach the maximum CRP value." (PMID 24286072, 2013). "Among REGARDS participants, 491 of 18,736 (2.6%) individuals with hsCRP≤3.0 mg/L developed sepsis, and 483 of 11,447 (4.2%) with CRP>3.0 mg/L developed sepsis." (PMID 23935961, 2013). "In particular, PCT and CRP, which have been most widely used in clinical treatment, have limited ability to distinguish sepsis from other inflammatory conditions or to predict outcome." (PMID 23935252, 2013). "A sepsis workup was obtained including a complete blood count, basic metabolic panel, C-reactive protein (CRP), urinalysis, and cultures of blood and urine." (PMID 23762715, 2013). "As expected, acute physiology and chronic health evaluation II (APACHE II) score, WBC counts, C-reactive protein and mortality were greater in the more severe stages of sepsis." (PMID 24144038, 2013).
Sepsis (continued). "A high C reactive protein, despite having a low specificity, was used as an indicator of severe sepsis." (PMID 23286235, 2013). "From the available research, there seem to be appropriate recommendations for the use of CRP in sepsis patients." (PMID 23869218, 2013). "The optimal cut-offs for PTX3, PCT and CRP in predicting severe sepsis between day 0 and day 28 and case fatality were estimated using ROC curves and Youdeńs index." (PMID 23341967, 2013). "In our opinion this does not represent a major limitation, since biomarkers, including LBP and CRP, were found to be the highest on the third day after the onset of sepsis." (PMID 24349403, 2013). "CRP is a biomarker involved in more than one inflammatory cascade amplification, now widely applied to sepsis diagnosis." (PMID 23935252, 2013). "These guidelines recommend starting antibiotics in any neonate who has clinical signs of sepsis but to repeat a CRP measurement 18 – 24 hours after starting treatment, to determine those infants who truly do have sepsis." (PMID 24359288, 2013). "Till now, a large number of markers have been proposed for early diagnosis of sepsis, especially C-reactive protein (CRP) and procalcitonin (PCT)." (PMID 23984377, 2013). "Outside anecdotal reports, we are not aware of published systematic evaluations of the impact of abnormal WBC indices on CRP rise with culture-proven sepsis." (PMID 24244325, 2013). "Its usefulness over markers like TC, ESR and CRP has been described in several conditions like sepsis, upper respiratory tract infections, pneumonias, pancreatitis, pyelonephritis, burns and in various other conditions." (PMID 23826894, 2013). "SAA is also an acute phase reactant like PCT and CRP, which has been proven to be a prognostic marker in late-onset sepsis in preterm infants." (PMID 23984377, 2013). "ROC analyses were performed to compare the diagnostic performance of four clinical parameters of their predictive potential for sepsis: IG#, CRP, LBP and IL-6." (PMID 23398965, 2013). "Using ROC analysis we found the IG count a superior biomarker for sepsis compared to C-reactive protein, lipopolysaccharide binding protein and interleukin-6." (PMID 23398965, 2013). "In severe sepsis patients we found an inverse relation between de reactive hyperaemia measured and the CRP level detected in plasma at inclusion (r = −0.563, p = 0.010)." (PMID 23936333, 2013). "In the present study, we have shown the utility of a computerized CRP-based sepsis evaluation protocol to safely reduce antimicrobial use in the VLBW preterm infant." (PMID 24244325, 2013). "In a univariate model high PTX3, PCT and CRP values predicted severe sepsis when used as continuous or grouping variables." (PMID 23341967, 2013). "Conventional C-reactive protein assays have been used to detect or guide the treatment of acute sepsis." (PMID 23935961, 2013). "Neutrophil CD64 (nCD64) expression has been found to be a better diagnostic marker for sepsis than procalcitonin (PCT) and C-reactive protein (CRP) in adults and recently in children." (PMID 23452299, 2013). "The blood chemistry was also unremarkable, apart from a C reactive protein concentration of 312 mg/l (normal range 0–5 mg/l), indicating severe sepsis." (PMID 23286235, 2013). "The main finding of our study is that markers of inflammation and of the severity of illness, specifically CRP and albumin levels at discharge, correlate with long-term prognosis (up to 90 days) after a sepsis episode." (PMID 23555017, 2013). "Although severe sepsis/shock group had higher sCD163, CRP, and WBC levels, a comparison of such indicators across groups is devoid of such significance." (PMID 23935252, 2013). "In order to compare the performance of PTX3 with an established biomarker in SIRS and sepsis we compared PTX3 with CRP in the patients." (PMID 24039869, 2013).
Sepsis (continued). "In infants where sepsis was clinically suspected, postnatal CRP, white cell count and absolute neutrophil count were measured up to 48 hours of age." (PMID 23272177, 2012). "This implies that CRP would correctly identify close to three quarters of neonates with sepsis and would have 79.0% probability in excluding sepsis." (PMID 22958461, 2012). "The serum sCD163 and CRP levels in sepsis patients were significantly higher than those in the SIRS patients (P<0.01), but no marked differences were observed for PCT levels and WBCs between these two groups." (PMID 22911680, 2012). "Sepsis patients had significantly higher CRP and serum sCD163 levels, as well as APACHE II scores, than the SIRS patients (P < 0.05)." (PMID 23013330, 2012). "C-reactive protein and procalcitonin are the most widely used values, despite their limited ability to distinguish sepsis from other inflammatory conditions." (PMID 22706919, 2012). "The sCD163 levels in severe sepsis patients were markedly higher than those in moderate sepsis patients (P<0.0001), and similar trends were also observed for CRP and PCT levels and SOFA scores." (PMID 22911680, 2012). "Hs-CRP was significantly correlated with PCT in patients with positive blood culture sepsis (r=0.54, p<0.001), 12–24 hours after admission." (PMID 22708043, 2012). "The CRP level is widely used to detect bacterial infections in children with fever and in neonates with suspected sepsis." (PMID 22943554, 2012). "CRP level in 33.3% (4 of 12 neonate) of early onset sepsis and 57% (4 out 7 cases) of late onset sepsis were upper than cut-off value." (PMID 23493845, 2012). "suPAR concentrations were closely related to other sepsis markers, including CRP, PCT, and tumor necrosis factor α levels." (PMID 22221662, 2012). "The results demonstrate that impedance aggregometry using collagen as the activator was a better biomarker for the diagnosis of severe sepsis in critical illness than procalcitonin, interleukin 6 and C-reactive protein." (PMID 23088388, 2012). "At the 2nd week, the period at which the frequency of sepsis and low T3 rate were the highest, serum T3 level was negatively correlated with IL-6 (r=-0.49, p=0.001) and CRP (r=-0.33, p=0.03) levels." (PMID 22672862, 2012). "Clinical signs of systemic inflammation including changes in body temperature, tachycardia and routine laboratory tests like leukocytosis and C-reactive protein (CRP) are used for diagnosis of sepsis." (PMID 23493845, 2012). "Taking all these results into consideration, it appears that suPAR has poor accuracy in diagnosing sepsis compared to CRP and PCT, making suPAR of limited value as a diagnostic marker of sepsis." (PMID 22221662, 2012). "Univariate analysis showed that amongst the clinical and biological parameters, only fluid balance and CRP were significantly higher in sepsis." (PMID 22719987, 2012). "CRP directly influences several stages of sepsis via complement activation, lipid accumulation and thrombosis." (PMID 23091606, 2012). "But in suspected sepsis 17% of cases and in the control group only in 5% of infants, CRP level was located higher than the cut-off value." (PMID 23493845, 2012). "Serum sCD163 is superior to PCT and CRP for the diagnosis of sepsis and differentiate the severity of sepsis." (PMID 22911680, 2012). "For the diagnosis of sepsis, the areas under the ROC curves for the initial levels of sCD163, CRP, and PCT were, respectively, 0.856 (95% CI: 0.791–0.921), 0.696 (0.595–0.797), which showed a more favorable performance for sCD163." (PMID 22911680, 2012). "We collected information from the hospital records of 91 neonates with suspected sepsis and of 152 febrile children with suspected infection on the number of ordered CRP tests, the number of EB-CRP tests, and the impact of the test results on decision-making." (PMID 22943554, 2012). "In infants with suspected neonatal sepsis, two CRP samples that are < 10 mg/l are useful in excluding sepsis." (PMID 23483792, 2012).
Sepsis (continued). "• Commonly used biomarkers, such as C-reactive protein and procalcitonin, are insufficiently sensitive or specific to stratify patients with sepsis." (PMID 22748193, 2012). "Serum T3 was negatively and more strongly correlated with IL-6 (r= -0.49, p= 0.001) and CRP (r=- 0.33,p= 0.03) at the 2nd week, at which time sepsis frequency and low T3 rates were the highest." (PMID 22672862, 2012). "The two biomarkers that have been most widely studied and used in patients with sepsis are C-reactive protein (CRP) and procalcitonin (PCT)." (PMID 22221662, 2012). "For the 91 NICU admissions, 263 CRP tests were performed during the initial work up of suspected neonatal sepsis episodes." (PMID 22943554, 2012). "The composite outcome included bacteriologic relapse with the same organism, a recurrent episode of illness with an elevation in serum C-reactive protein, or a subsequent clinical diagnosis of sepsis by a blinded adjudication committee." (PMID 22085732, 2011). "LBP and CRP plasma concentrations, assessed in intervals of 24 hours and more, rather show a very similar kinetics in the course of sepsis." (PMID 21901123, 2011). "One study indicated that IL-6 along with the other inflammatory marker C-reactive protein (CRP) levels predicted that a baby was more likely to be born with sepsis and that the time to delivery was related to these factors as well." (PMID 22114461, 2011). "There was a strong concordance of day-to-day changes of CRP levels (n = 242) with the associated LBP changes for all patients and time points studied during the first 14 days of sepsis." (PMID 21901123, 2011). "The relationship between CRP and kidney-dysfunction free days was significantly modified by sepsis (interaction P = 0.01)." (PMID 21366899, 2011). "In summary, sTREM-1 levels can reflect sepsis severity more accurately than CRP and PCT and the dynamic changes of sTREM-1 are more sensitive for predicting prognosis." (PMID 21356122, 2011). "Binary logistic regression analysis showed that SC (OR 164.6; 95% CI 21.6–1255.1; P < .001) and CRP (OR 1.1; 95% CI 1.0-1.1; P = .007) were predictors of sepsis in our population." (PMID 21765851, 2011). "In the present study, we clearly demonstrate that CRP, a major acute phase reactant protein, increases markedly in profoundly immunosuppressed cancer patients with sepsis." (PMID 21595932, 2011). "During the first week of sepsis, both CRP and LBP showed the highest plasma levels at d2 or d3 after onset of sepsis with median values above 100 mg/L and 50 mg/L, respectively, in both groups (S and NS)." (PMID 21901123, 2011). "Association of CRP and LBP changes in the plasma concentration from one time point of observation to the other during 14 days after onset of sepsis." (PMID 21901123, 2011). "Because the BNP level can increase in patients with sepsis, our results suggest that measuring both CRP and BNP can eliminate this drawback to the measurement of BNP alone." (PMID 21696613, 2011). "In conclusion, our study demonstrates that LBP and CRP plasma concentrations are well correlated with each other and change concordantly in the course of sepsis." (PMID 21901123, 2011). "The obtained AUC of suPAR for predicting sepsis in critically ill patients at admission to the ICU was low compared with CRP and PCT." (PMID 21324198, 2011). "Many serum markers have been assessed in sepsis; procalcitonin and CRP being the more extensively studied." (PMID 21762483, 2011). "Due to a broad overlap between S and NS both in LBP and CRP plasma concentrations during the first 5 days of sepsis, their predictive accuracy for mortality (at day 28) as assessed by ROC-analysis was very poor (AUC<.55)." (PMID 21901123, 2011). "Hazard ratio was 1.037 per 0.1 increases for CRP/prealbumin when adjusted for age, gender, sepsis and SOFA." (PMID 21714897, 2011).
Sepsis (continued). "C-reactive protein (CRP) is a well established parameter to detect local infection and has also been used for many years in monitoring the inflammatory response to sepsis." (PMID 21901123, 2011). "Although C-reactive protein (CRP) has been widely used as a prognostic marker in infectious diseases, its prognosic value in bacteremia and sepsis is weak." (PMID 21423699, 2011). "Comparisons are also made among sTREM-1, WBC counts, serum CRP, serum procalcitonin (PCT), urine output, creatinine clearance (CCr), SCr, and blood urea nitrogen (BUN) among sepsis patients, in an effort to define relevant diagnostic values." (PMID 22023777, 2011). "The lysis index proved to be a better biomarker for sepsis in critical illness than procalcitonin, interleukin 6, or C-reactive protein." (PMID 20929576, 2010). "Elevated serum NGAL is independently related to the severity of AKI (cystatin C and renal SOFA), but also to the presence of sepsis and the extent of systemic inflammation (CRP)." (PMID 20122150, 2010). "PCT and CRP have been most widely used, but even these have limited abilities to distinguish sepsis from other inflammatory conditions or to predict outcome." (PMID 20144219, 2010). "A CRP level of 50 mg/l or more has been reported as highly suggestive of sepsis, while the combination of a CRP level of 50 mg/l or more with systemic inflammatory response syndrome was identified as the best model to diagnose infection at ICU admission." (PMID 21034463, 2010). "Although CRP is often reported as inferior compared with PCT in terms of sepsis diagnosis, it is frequently used in clinical practice because of its greater availability." (PMID 20144219, 2010). "CRP, IL-6 blood level, and mortality were significantly higher in the septic shock group (n = 57) than in the sepsis group (n = 127) (P < 0.001)." (PMID 20202204, 2010). "In the presence of SIRS or sepsis, CRP, IL-6, IL-10, Prognostic Inflammatory and Nutritional Index (NI), and triglycerides—but not glucose, VO2, or VCO2 increased significantly." (PMID 20490277, 2010). "Established biomarkers for the diagnosis of sepsis are procalcitonin, interleukin 6, and C-reactive protein." (PMID 20929576, 2010). "A number of acute-phase proteins, such as C-reactive protein (CRP) and fibrinogen, rise after serious injury or sepsis in association with a drop in serum albumin, transthyretin, and transferrin." (PMID 20490277, 2010). "In both postoperative and sepsis patients, mean values for procalcitonin, interleukin 6, and C-reactive protein exceeded the reference interval by far." (PMID 20929576, 2010). "The thromboelastometry lysis index proved to be a more reliable biomarker of severe sepsis in critically ill adults than were procalcitonin, interleukin 6, and C-reactive protein." (PMID 20929576, 2010). "In bacteremia and sepsis, the results concerning CRP as a predictor of clinical outcome are controversial." (PMID 20500875, 2010). "Results demonstrated that CRP level was significantly higher in the septic shock group than in the sepsis group." (PMID 20202204, 2010). "The diagnosis of sepsis is based on clinical symptoms, although several endogenously produced proteins, such as procalcitonin or C-reactive protein (CRP), have been proposed as markers of infection and are used in clinical practice." (PMID 20098709, 2010). "PCT and CRP have been most widely used, but even these have limited ability to distinguish sepsis from other inflammatory conditions or to predict outcome." (PMID 20144219, 2010). "Increased serum LBP levels have been reported in neonatal early onset sepsis, and is reported to be a better marker in critically ill neonates and children than other markers, such as C-reactive protein, procalcitonin and interleukin-6 (IL-6)." (PMID 20158885, 2010). "It has previously been suggested that serial elevated CRP levels are more appropriate than a single CRP measurement in diagnosing sepsis." (PMID 19152691, 2009).